CRNDE (colorectal neoplasia differentially expressed)
Synonyms: LOC643911; LINC00180; CRNDEP; NCRNA00180; PNAS-108; lincIRX5; LOC101927480
Gene: Long non-coding RNA gene on chromosome 16 (54,844,649 to 54,931,354, reverse strand). Ensembl gene ENSG00000245694.
Gene Ontology:
Biological process: SRP-dependent cotranslational protein targeting to membrane, signal sequence recognition
Cellular component: signal recognition particle, endoplasmic reticulum targeting
Diseases named in the same sentence as CRNDE in open-access papers:
CRNDE is named in the same sentence as 59 diseases in open-access papers, as found by Europe PMC text mining. Sharing a sentence is not in itself a finding about the gene and the disease. The quoted sentences say what the papers report.
glioma (45 papers, 2014 to 2025). A benign or malignant brain and spinal cord tumor that arises from glial cells (astrocytes, oligodendrocytes, ependymal cells). "Another tumor oncogene, CRNDE, which is also among the most upregulated lncRNAs in glioma, has been associated with tumor progression." (PMID 32650527, 2020). "Other mechanisms have been proposed to also underlie the oncogenic role of CRNDE in glioma." (PMID 29152149, 2017). "A recent study has shown that a transcript variant of lnc-IRX3-4 (often called CRNDE), most significantly upregulated in gliomas, promotes tumor cell growth and invasion, indicating that it may serve as a novel therapeutic target." (PMID 26918340, 2016). "Long non-coding RNAs (lncRNAs) such as MEG3 and CRNDE are also dysregulated in glioma tissues and may be associated with the stemness of glioma cells." (PMID 25191339, 2014). "They linked some previously glioma-associated lncRNAs, like H19, CRNDE, and HOTAIRM1, with recurrence, and also defined new lncRNAs, like AC016745.3, XLOC_001711, and RP11-128A17.1, which their lncRNA–mRNA co-expression analysis indicated might have critical roles in glioma recurrence." (PMID 32650527, 2020). "CRNDE, first identified in colorectal cancer, is significantly upregulated in gliomas and correlates with increased tumour grade and diminished survival." (PMID 41154382, 2025). "Among the model genes, CRNDE, a long non-coding RNA, is upregulated in various solid tumors and promotes malignant progression of glioma by regulating the miR-384/PIWIL4/STAT3 axis." (PMID 40130175, 2025). "At the same time, our experimental results also confirmed down-expression of CRNDE in U-118MG and U251 cells markedly inhibited glioma cell proliferation and migration capabilities." (PMID 37934582, 2023). "Previous studies have reported that CRNDE is a proto-oncogene that is expressed in gliomas and that its expression is negatively correlated with the prognosis of tumor." (PMID 35359568, 2022). "We found that the expression of LINC00641 in glioma cells was significantly lower than that in normal astrocytes, and the expression of CRNDE and LNCTAM34a was significantly higher in glioma cells." (PMID 35311131, 2022). "The results indicated that LINC0090, MIR155JG and CRNDE were significantly upregulated in glioma samples, and TTC28.AS1and WAC.AS1 were downregulated." (PMID 35237509, 2022). "CRNDE was also found to regulate the occurrence and development of glioma through the TLR3-NF-κB-cytokine signaling pathway." (PMID 33767729, 2021). "Knockdown of CRNDE induced glioma cell apoptosis, while overexpression of CRNDE promoted U87 and U251 cell proliferation, migration and invasion." (PMID 34425834, 2021). "Knockdown of CRNDE attenuates cell growth and migration in vitro and prevents glioma growth in vivo, suggesting that CRNDE functions as an oncogene." (PMID 33800703, 2021). "For example, lncRNA CASC2 negatively regulates miR-21 to suppress cell growth of glioma, whereas lncRNA CRNDE promotes glioma cell growth and invasion through mTOR signaling." (PMID 34194477, 2021). "Compared with the normal gliocyte (NHA) cells, the levels of CRNDE were significantly upregulated in all glioma cell lines, especially in PGC cells (P < 0.05)." (PMID 34454479, 2021). "The expression of CRNDE was found to be significantly up-regulated in glioma tissues (P < 0.001), and the expression level was positively correlated with the pathological grading of WHO stage (P < 0.05)." (PMID 34454479, 2021). "Four transcript variants of human CRNDE are listed by the National Center for Biotechnology Information, and all of these are upregulated in glioma cells, compared to normal control cells, which suggests that CRNDE has a role in glioma formation." (PMID 32650527, 2020). "Multiple lncRNAs have been reported to be involved in the initiation and progression of glioma, which include CRNDE, H19 and XIST, GAS, Malat1, Hotair, and SOX2ot." (PMID 31052326, 2019).
glioma (continued). "Together with H19 and HOTAIRM1, CRNDE was also found among lncRNAs upregulated in recurrent gliomas." (PMID 30217088, 2018). "CRNDE overexpression promotes glioma cell growth and migration in vitro and tumorigenesis in a xenograft mouse model." (PMID 30116729, 2018). "CRNDE expression is significantly up-regulated in a number of neoplastic diseases, such as colorectal cancer and glioma." (PMID 28178668, 2017). "Taken together, these data suggest that CRNDE binds to miR-136-5p and negatively regulates its expression in glioma cells." (PMID 29152149, 2017). "Our results suggest that CRNDE functions as a ceRNA to promote glioma malignancy by indirectly inducing Bcl-2 and Wnt2 expression through binding and repression of miR-136-5p." (PMID 29152149, 2017). "This evidence, as well as the present results highlight the relevance of CRNDE in glioma, by implying that a single lncRNA controls the activity of multiple miRNAs, conceivably affecting the expression of a large number of genes." (PMID 29152149, 2017). "Forced overexpression of CRNDE have resulted in increased glioma cell growth and migration, while knockdown of CRNDE would suppress oncogenic activities." (PMID 26230711, 2015). "CRNDE was overexpressed in all glioma cell lines, and FOXD2-AS1 was overexpressed in U251 cells." (PMID 37152037, 2023). "Based on these results, we speculated that lncRNA CRNDE played a role as an oncogene in glioma, and might through targeting miR-23b-3p regulating IDH1, which is the focus of our future work." (PMID 37934582, 2023). "Similarly, the lncRNAs MIR210HG, LINC01503, CRNDE, HOXC-AS1 and MIR22HG were found to play an essential role as risk factors in prolonging the survival time of glioma patients also in high agreement with our findings." (PMID 37934582, 2023). "Thus, here we checked m6A modifications of previously reported glioma associated lncRNAs: MALAT1, NEAT1, XIST1, TUG1, CRNDE, LINC00461, and HOTTIP." (PMID 35361860, 2022). "First, CRNDE regulates pivotal signaling pathways of tumorigenesis in gliomas." (PMID 35402077, 2022). "Moreover, CRNDE also acted as a ceRNA that bound to and negatively regulated miR-136-5p in glioma, subsequently protecting Bcl-2 and Wnt2 from miR-136-5p-mediated inhibition." (PMID 32435153, 2020). "LncRNAs that are involved in both embryogenesis and glioma biology (e.g: CRNDE, HOTAIRM1, ADAMTS9‐AS2), with expression levels controlled by epigenetic mechanisms, could represent a future option for further studies on epigenetic therapy for glioma patients." (PMID 30117678, 2018). "Overexpression of CRNDE in glioma could promote cell proliferation and invasion in vitro and tumorigenesis in vivo, suggesting CRNDE’s role in glioma biology." (PMID 30217088, 2018). "We therefore propose that CRNDE functions as a competing endogenous RNA (ceRNA) that binds to and negatively regulates miR-136-5p, thereby protecting Bcl-2 and Wnt2 from miR-136-5p-mediated inhibition in glioma." (PMID 29152149, 2017). "In addition, the expression profiles analysis in recurrent gliomas compared with primary gliomas identified abundant differentially expressed lncRNAs, such as H19, CRNDE, and HOTAIRM1." (PMID 28293170, 2017). "Our in vitro experiments in glioma cells confirmed that changes in the expression of CRNDE and miR-136-5p result in changes in Wnt2 and Bcl-2 expression at the mRNA and protein levels, although our study did not provide direct evidence for the corresponding miRNA/mRNA interactions." (PMID 29152149, 2017). "Moreover, in glioma, miR-136-5p, miR-384 and miR-186 could be negatively regulated by CRNDE to facilitate cancer cells growth." (PMID 32435153, 2020).
glioma (continued). "Indeed, CRNDE expression is also overexpressed in many other cancers including glioma." (PMID 26230711, 2015). "When the “old” classification was used, the expression of CRNDE, FREM2, and SPRY genes allowed the diagnosis of “glioblastoma, grade IV” to be differentiated from the lower grade gliomas (astrocytomas, oligoastrocytomas, and oligodendrogliomas)." (PMID 36613601, 2022). "It has been confirmed that LncRNAs can function as molecular signaling mediators to regulate glioma phenotypes through mediating the expression of genes in NEAT1-WNT/β catenin 27 and CRNDE- mTOR signaling pathway." (PMID 34093827, 2021). "The presence of several lncRNAs like CRNDE, HOTAIRM1 and H19 among the upregulated transcripts, were in concordance with earlier reports on their oncogenic role in glioma." (PMID 30038703, 2018). "For example, lncRNAs, such as HOTAIR, CRNDE, GAS5 and other lncRNAs with abnormal expression in glioma tissues and cell lines, regulate the biological behaviors of glioma cells." (PMID 29132362, 2017). "Overall, the study constructed a prognostic model in glioma, and predicted a lncRNA CRNDE/miR-23b-3p/IDH1 axis, which could potentially be useful for gene therapy of glioma." (PMID 37934582, 2023). "Although CRNDE was originally identified to be specifically high-expressed in CRC, overexpressed CRNDE was also observed in other cancers, such as glioma, hepatocellular carcinoma (HCC), lung cancer, breast cancer (BC), gastric cancer (GC), and renal cell carcinoma (RCC)." (PMID 32435153, 2020). "High-throughput transcriptome analyses of glioma tissues/cells identified numerous highly and/or differentially expressed lncRNAs, including MALAT1, HOXA11-AS, and CRNDE, which correlate with histological and molecular subclassification, and/or show prognostic values." (PMID 30116729, 2018). "Importantly, identification of key lncRNAs involved in neurogenesis and normal brain development (e.g CRNDE, HORAIRM1 and TUNA) as the most dysregulated lncRNAs in glioma suggests aberrant reactivation as a mechanism that promotes oncogenesis." (PMID 30117678, 2018). "Interestingly, lncRNA HNF1A-AS1, lncRNA CCND2-AS1, lncRNA CRNDE, lncRNA CASC2 were revealed that promotional effects on cell proliferation via activation of Wnt/β-catenin cascade in osteosarcoma, glioma, colorectal cancer and bladder cancer were documented, respectively." (PMID 29453409, 2018).
colorectal cancer (19 papers, 2012 to 2025). A primary or metastatic malignant neoplasm that affects the colon or rectum. "Of these nineteen lncRNAs, miR-215, FOXD2-AS1, SATB2-AS1, TP53TG1, LINC01224, CRNDE, and DPP10-AS1 have been implicated in colorectal cancer (CRC)." (PMID 38666928, 2024). "CRNDE is an oncogenic lncRNA located at an atypical locus—hCG_1815491 on chromosome 16—and was activated early in colorectal cancer." (PMID 33924522, 2021). "CRNDE is an lncRNA located on chromosome 16, which was first found to be upregulated in colorectal cancer." (PMID 33767729, 2021). "For example, lncRNA Colorectal Neoplasia Differentially Expressed (CRNDE) is upregulated in colorectal cancer (CRC) tissues and the depletion of CRNDE notably represses proliferation while enhances apoptosis of CRC cells both in vitro and in vivo." (PMID 33292252, 2020). "In previous studies, CRNDE expression is significantly up-regulated in a number of neoplastic diseases, including colorectal cancer." (PMID 27637083, 2016). "Colorectal Neoplasia Differentially Expressed (CRNDE), which is located on chr16:54,952,777–54,963,101, is the most up-regulated lncRNA in colorectal cancer." (PMID 27637083, 2016). "CRNDE was initially identified as a lncRNA whose expression is highly elevated in colorectal cancer, but it is also upregulated in many other solid tumors and in leukemias." (PMID 23226159, 2012). "Some reports had proved lncRNA CRNDE could promote AML cell proliferation; and lncRNA CRNDE also promoted colorectal cancer cell proliferation, chemoresistance, and it attenuated chemoresistance in gastric cancer." (PMID 34996458, 2022). "CRNDE is over-expressed in colorectal carcinomas and promotes in vitro and in vivo growth and invasion of CRC cells." (PMID 29137379, 2017).
Sepsis (8 papers, 2020 to 2022). Sepsis is defined as life-threatening organ dysfunction caused by a dysregulated host response to infection. "It was observed that MALAT1 and CRNDE were inversely and significantly correlated with each other across both sepsis and control plasma samples." (PMID 35300579, 2022). "Our study also observed CRNDE downregulation in patients with sepsis and the inhibitory effects of CRNDE on LPS-induced HBEpC apoptosis." (PMID 35300579, 2022). "We first examined changes in MALAT1 and CRNDE levels in plasma samples from both sepsis patients (n = 60) and healthy controls (n = 60) using RT-qPCR." (PMID 35300579, 2022). "Significantly, Cheng and his colleagues recently found five lncRNAs (FENDRR, MALAT1, TUG1, CRNDE, and ANCR) were correlated with sepsis-associated mRNA modules perhaps by acting as competing endogenous RNAs (ceRNAs)." (PMID 34483898, 2021). "In one previous study, five lncRNAs, including FENDRR, MALAT1, TUG1, CRNDE, and ANCR, were associated with sepsis." (PMID 34483898, 2021). "Both MALAT1 and CRNDE regulate ten sepsis modules and they share seven common modules, six out of them are down-regulated." (PMID 32471511, 2020). "MALAT1 is upregulated in sepsis and CRNDE is downregulated in sepsis." (PMID 35300579, 2022). "This study explored the interaction between MALAT1 and CRNDE in sepsis." (PMID 35300579, 2022). "We found that MALAT1 was upregulated and CRNDE was downregulated in sepsis." (PMID 35300579, 2022). "Therefore, this study was carried out to analyze the roles of MALAT1 and CRNDE in sepsis and to explore their potential interactions." (PMID 35300579, 2022). "Another study showed that lncRNA CRNDE was down-regulated in the CLP model of sepsis in rat." (PMID 36386180, 2022). "After proper treatment, MALAT1 was downregulated and CRNDE was upregulated in sepsis." (PMID 35300579, 2022). "Therefore, we hypothesized that MALAT1 might interact with CRNDE to participate in LPS pathways involved in sepsis." (PMID 35300579, 2022). "Therefore, CRNDE may participate in sepsis through the LPS-dependent pathway to play protective roles." (PMID 34872438, 2021). "Therefore, altered expression of MALAT1 and CRNDE may participate in sepsis." (PMID 35300579, 2022). "The lncRNA MALAT1 can alleviate sepsis in burn-injured patients by regulating miR-214/TLR5; the lncRNA CRNDE is involved in aggravating the inflammatory process of sepsis through the miR-181a-5p/TLR4 axis." (PMID 36274974, 2022). "RT-qPCR analyses showed that MALAT1 was upregulated, while CRNDE was downregulated in sepsis and overexpression of MALAT1 and CRNDE downregulated the expression of each other." (PMID 35300579, 2022). "Therefore, MALAT1 and CRNDE may participate in sepsis in a LPS-dependent manner." (PMID 35300579, 2022). "They identified five sepsis-related lncRNAs, including FENDRR, MALAT1, TUG1, CRNDE, and ANCR, whose functions were highly related with biological processes of sepsis." (PMID 34055659, 2021). "Previous studies have shown that both lncRNAs Colorectal Neoplasia Differentially Expressed (CRNDE) and taurine-upregulated gene 1 (TUG1) play protective roles in sepsis-induced kidney injury." (PMID 34872438, 2021). "Five lncRNAs, FENDRR, MALAT1, TUG1, CRNDE, and ANCR, were detected as sepsis regulators based on the interactions among lncRNAs and the identified coexpression modules." (PMID 32471511, 2020). "We identified five sepsis lncRNAs, FENDRR, MALAT1, TUG1, CRNDE, and ANCR, all of which connect five or more sepsis modules, indicating their functions are highly related with biological processes of sepsis." (PMID 32471511, 2020). "Although most of the lncRNAs regulate none or merely a single sepsis module, FENDRR, MALAT1, TUG1, CRNDE, and ANCR connect multiple sepsis modules with the connectivity of 14, 10, 10, 8, and 5, respectively, which are expected to have high potentials to be involved in the sepsis progress." (PMID 32471511, 2020).
Sepsis (continued). "Five sepsis lncRNAs were ultimately identified, FENDRR, MALAT1, TUG1, CRNDE, and ANCR." (PMID 32471511, 2020). "Although we failed to explore the in vivo crosstalk between them, we showed that CRNDE and TUG1 were positively correlated across plasma samples from both sepsis patients and healthy controls, suggesting the existence of the positive feedback loop in both sepsis patients and healthy controls." (PMID 34872438, 2021). "Furthermore, we found that CRNDE and MALAT1 may act as miRNA sponges of sepsis related miRNAs to regulate the expression of sepsis modules." (PMID 32471511, 2020). "Therefore, CRNDE and TUG1 may postively regulate each other to inhibit cell apoptosis in sepsis." (PMID 34872438, 2021).
hepatocellular carcinoma (7 papers, 2018 to 2023). A malignant tumor that arises from hepatocytes. "Based on above results, we hypothesized that the development of hepatocellular carcinoma might be closely related to the overexpression of CRNDE and low expression of miR‐217." (PMID 30246921, 2018). "Colorectal Neoplasia Differentially Expressed (CRNDE), which was originally found aberrantly expressed in CRC, is upregulated in a number of malignant cancers such as pancreatic, lung, and hepatocellular cancers." (PMID 31275444, 2019).
acute myeloid leukemia (6 papers, 2012 to 2024). Acute myeloid leukemia (AML) is a group of neoplasms arising from precursor cells committed to the myeloid cell-line differentiation. "Expression of CRNDE is also shown to be upregulated in adult acute myeloid leukemia (AML) patients and was associated with lower complete remission and shorter event free survival." (PMID 38336706, 2024). "Intriguingly, high CRNDE expression has also been associated with good survival in THYM and acute myeloid leukemia (AML)." (PMID 35402077, 2022). "Although CRNDE is highly expressed in acute myeloid leukemia (AML), its mechanism of action remains unknown." (PMID 34408205, 2021). "While moderately upregulated in most acute myeloid leukemias (AML), CRNDE expression is particularly elevated in FAB Type M2 AML and in promyelocytic Type M3 AML." (PMID 23226159, 2012). "lncRNA CRNDE which was highly elevated in many solid tumors and in acute myeloid leukemias (AML) can promote cell growth and suppress apoptosis, which supports a role for CRNDE as a mediator of oncogenesis." (PMID 25435812, 2014). "A recent study found that lncRNA CRNDE is highly elevated in many solid tumors and in acute myeloid leukemias (AML), especially in M2 AML and M3 AML, and lncRNA CRNDE can promote cell growth and suppress apoptosis, which supports a role for CRNDE as a mediator of oncogenesis." (PMID 23725405, 2013).
breast carcinoma (6 papers, 2015 to 2020). "CRNDE has also been identified as an oncogene, activating the Wnt signaling pathway in breast cancer by sponging miR-13624." (PMID 31863035, 2019).